CD34 (CD34 molecule)
Diseases named in the same sentence as CD34 in open-access papers (continued):
Sharing a sentence is not in itself a finding about the gene and the disease.
heart failure (continued). "TdTomato+ cells that were isolated from heart failure mouse expressed higher levels of fibroblastic markers and ECM proteins but less levels of CD34." (PMID 36805782, 2023). "In contrast, CD34+ cells can accelerate the accumulation of lipids in the heart by differentiating into FABP4+ fibroblasts, resulting in lipid toxicity that leads to the progression of heart failure." (PMID 39198543, 2024). "Taken together, CD34+ cells can accelerate the accumulation of lipids in the heart by differentiating into FABP4+ fibroblasts, resulting in lipid toxicity, which leads to the progression of heart failure." (PMID 39198543, 2024). "Interestingly, several paracrine factors relevant in the pathophysiology of heart failure, including IL6, IL10, NPPA and NPPB, were also expressed at higher levels in SSEA4+CD34- cells." (PMID 35709180, 2022). "Nevertheless, norepinephrine failed to increase CD34+ levels in heart failure patients." (PMID 20525353, 2010). "To investigate these questions, we have isolated and analyzed human SSEA4+CD34-, SP and C-kit+CD45- cells from patients undergoing heart transplantation due to heart failure, as well as from donors not suffering from heart failure." (PMID 35709180, 2022).
sickle cell disease (25 papers, 2011 to 2025). Sickle cell anemias are chronic hemolytic diseases that may induce three types of acute accidents: severe anemia, severe bacterial infections, and ischemic vasoocclusive accidents (VOA) caused by sickle-shaped red blood cells obstructing small blood vessels and capillaries. "Single infusion of CRISPR/Cas9‐edited sickle allele‐modified differentiated cluster (CD34+) hematopoietic stem progenitor cells (HSPC) in subjects with severe sickle cell disease (SCD) aged ≥12–35 years." (PMID 39081515, 2024). "We performed gene-targeting experiments by electroporating HiFi Cas9 and HBB-specific chemically modified guide sgRNAs46 into primary CD34+ HSPCs isolated from patients with sickle cell disease (which contained the E6V point mutation)." (PMID 33473139, 2021). "CD34+ cells from the mPB of a patient with transfusion-dependent β-thalassemia and CD34+ cells from the bone marrow of a patient with sickle cell disease were transduced with recombinant LVV encoding the human β-globin gene in the presence or absence of PGE2." (PMID 29102562, 2018). "Even the recovery of CD34+ cells for gene therapy, using granulocyte-colony stimulating factor (G-CSF) stem cell mobilization may be harmful in β-thalassemia patients, and may cause severe side effects in sickle cell anemia patients." (PMID 21569277, 2011). "In some studies, the CRISPR-Cas9 technique has been utilized to target BCL11A enhancers in CD34+ cells, which were subsequently reintroduced into patients with β-thalassemia and sickle cell disease, leading to successful treatment 52,53." (PMID 40083704, 2025). "To demonstrate the potential of our clonal expansion concept in the human setting, we edited healthy cord blood (CB)-derived CD34+CD45RA− human HSCs (huHSCs) at the HBB locus to knock in a two-base mutation, creating a sickle cell disease (SCD)-like genotype." (PMID 37385251, 2023). "The first CRISPR clinical trial in the US was initiated in 2018 and involved use of autologous CD34+ HSPCs modified with CRISPR-Cas9 to upregulate the expression of fetal hemoglobin as a treatment for sickle cell disease and β-thalassemia (NCT03655678)." (PMID 32977396, 2020). "The Sleeping Beauty transposon system not only supports the efficient gene transfer into mobilized CD34+ HSCs, but also into human cord blood CD34+ cells as shown in a model of sickle cell disease." (PMID 30899334, 2019). "We observed elevated levels of vector-derived β-globin in BFU-E derived from CD34+ cells transduced with LVV in the presence of 10 μM PGE2 in the context of both sickle cell disease and thalassemia CD34+ cells." (PMID 29102562, 2018). "Transduction efficiency was consistently increased in primary CD34+ cells from multiple normal human donors and from patients with β-thalassemia or sickle cell disease." (PMID 29102562, 2018). "The semi-automated process was then expanded for BM CD34+ cell products, which are used in gene therapy for very young patients and/or disease settings where mobilization is contraindicated, such as FA and sickle cell disease." (PMID 27762266, 2016). "In summary, LIN28A-OE reduced let-7 miRNAs levels and increased HbF expression in erythroblasts cultured from CD34(+) cells from pediatric sickle cell anemia donors' blood at magnitudes similar to those previously reported using cells from healthy adults." (PMID 25188417, 2014). "The hematopoietic differentiation potential was compared between 12 iPS cell lines generated from normal amniotic fluid cells or from homozygous sickle cell anemia (HbS), endothelial progenitor cells from normal peripherical blood and CD34+ from normal cytapheresis or BM." (PMID 26938212, 2016). "Insulators combined with the erythroid-specific IHK promoter could potentially confer long-term therapeutic levels of hemoglobin for the treatment of sickle cell disease, β-thalassemia, and other hemoglobinopathies utilizing CD34+ cells." (PMID 22216176, 2011).
sickle cell disease (continued). "In humans, increased frequencies of CD34+ cells in PB are observed in many hematopoietic diseases, notably in sickle cell anemia and b-thalassemia, and in cardiovascular, autoimmune and rheumatological conditions, but with very few studies providing further resolution of CD34+ subsets." (PMID 35073399, 2022). "In the present study, we investigated whether the GGHI-mB-3D vector can also exhibit an equally therapeutic effect, following the transduction of sickle cell disease (SCD) CD34+ cells at MOI 100, leading to HbF increase coupled with HbS decrease, and thus, to phenotype improvement in vitro." (PMID 36560719, 2022). "This gene-editing strategy involves isolating CD34+ HSPCs from patients, gene modifying the cells ex vivo, and infusing them back into the patient for the treatment of HIV, sickle cell anemia, and β-thalassemia." (PMID 32977396, 2020). "In sickle cell disease, curative high levels of T-cell chimerism (>50%) using HLA-matched sibling allogenic CD34+ HSC transplantation can be achieved without myloablation." (PMID 21569277, 2011). "Here, we report that the proportions of Lin-CD34+38- hematopoietic multipotent cells (HMCs) and of Lin-CD34+CD38+ hematopoietic progenitors cells (HPCs) are highly variable between individuals but stable over long periods of time, in both healthy individuals and sickle cell disease (SCD) patients." (PMID 33003401, 2020). "Moreover, Vertex Pharmaceuticals Incorporated have proposed a phase 1/2 study to evaluate the safety and efficacy of autologous CRISPR-Cas9 Modified CD34+ Human Hematopoietic Stem and Progenitor Cells (hHSPCs) using CTX001 in subjects with severe sickle cell disease (NCT03745287)." (PMID 31754267, 2020). "However, since G-CSF is unsafe and contraindicated in patients with sickle-cell disease, robust and rapid stem cell mobilization regimens lacking G-CSF are needed for autologous gene therapy for patients with sickle cell anemia, which may require >20 × 106 CD34+/kg." (PMID 39199390, 2024).
spindle cell lipoma (25 papers, 2011 to 2025). A benign circumscribed tumor composed of spindled cells, adipocytes, and collagen bundles. "In the present case, microscopic analysis revealed a well-circumscribed, low-fat variant of spindle cell lipoma showing diffuse CD34 positivity and a Ki-67 index below 1%, confirming its benign nature and excluding malignant mimics." (PMID 41283482, 2025). "Pathologically, collagen fibers, capillaries, small vessels, and CD34‐positive spindle cells were dispersed among mature adipose tissues, indicative of spindle cell lipoma." (PMID 39780903, 2025). "Histopathological analysis revealed a spindle cell lipoma characterized by CD34 positivity and a Ki-67 proliferation index of less than 1%." (PMID 41283482, 2025). "The pathological diagnosis was spindle cell lipoma in three patients of which two were reported to show CD34‐positive spindle cells (Cases 3 and 4)." (PMID 39780903, 2025). "Chondroid lipomas can be confused with spindle cell lipomas, which primarily occur on the back or posterior neck, display CD34 expression, and feature deletions involving 13q and 16q." (PMID 40729281, 2024). "The immunohistochemical profile revealed positivity of spindle cells for CD34, negativity for S100, and low proliferation with Ki67, which confirmed the diagnosis of spindle cell lipoma and revealed its benign behavior." (PMID 33950973, 2021). "Oral spindle cell lipoma is composed by variable amounts of mature adipocytes, CD34-positive spindle cells and mast cells in a background of myxoid and collagenous connective tissue." (PMID 32851988, 2021). "The immunohistochemical profile revealed positivity of spindle cells for CD34, negativity for S100, and a low proliferation with Ki-67, which confirmed the diagnosis of spindle cell lipoma and revealed its benign behavior." (PMID 33950973, 2021). "In spindle cell lipoma, a benign tumour described in 1975, TCs/CD34+SCs and mature adipose tissue are the main components." (PMID 33353193, 2020). "As in spindle cell lipoma, these cells strongly express CD34 and negativity for S100 protein, desmin and αSMA." (PMID 33353193, 2020). "Other tumors, including spindle cell lipomas, fibromas, fibromyxomas and Kaposi sarcomas, also express CD34." (PMID 32516921, 2020). "The two DDLS cases in the present study were rich in spindle cell lipoma-like (spindle cell liposarcoma) areas with strong cytoplasmic CD34-positivity, as well as rich in lipoblasts." (PMID 25435981, 2015). "This tumor is most often confused with spindle cell lipoma, as both are spindle cell neoplasms, both are positive for CD34, and in addition at the molecular level, both reveal similar loss of genetic material from the 13q14 region." (PMID 26033228, 2015). "Both spindle cell lipoma and mammary-type myofibroblastoma are morphologically similar benign neoplasms, composed of CD34-positive spindle cells admixed with mature adipose tissue, and both reveal loss of genetic material from the chromosome 13q14 region." (PMID 26033228, 2015). "Spindle cell lipoma with myxoid change includes CD34-positive and bcl-2-positive spindle cells, which develop on endocapillary cells." (PMID 22185472, 2011). "While the presence of CD34-positive spindle cells is reminiscent of low-fat spindle cell lipoma, some benign FH may also express CD34 focal, which does not support the spindle cell lipoma diagnosis." (PMID 40376352, 2025). "The spindle cells were positive for CD34, indicative of spindle cell lipoma." (PMID 39780903, 2025). "Expression of CD34 is also observed in spindle cell lipoma, similar to fat-forming SFT." (PMID 38388450, 2024). "The combination of cervical localization, variable spindle cell histology, CD34 positivity, and loss of RB1 immunoexpression places branchioma, spindle cell lipoma (SCL), and spindle cell–predominant trichodiscoma (SCPT) in the most common differential diagnosis." (PMID 37401932, 2023).
spindle cell lipoma (continued). "Both lesions can have CD34+ cells, but spindle cell lipoma usually has strong CD34 expression." (PMID 36074249, 2023). "A previous case report noted a 48-year-old man with DFSP with fibrosarcomatous change and multiple spindle cell lipomas, and given the common denominator of CD34+ interstitial dendritic cells, this indicates that there may be a common cellular progenitor." (PMID 35573491, 2022). "Immunohistochemically, spindle cell lipoma is characterized by the diffuse expression of CD34." (PMID 33950973, 2021). "In this section, we present examples of benign tumours/pseudo-tumours of adipose tissue in which a greater number of TCs/CD34+SCs are observed, including spindle cell lipoma, dendritic fibromyxolipoma, pleomorphic lipoma, infiltrating angiolipoma of skeletal muscle and elastofibrolipoma." (PMID 33353193, 2020). "The spindle cells show reactivity with CD34 and SMA and partially resemble the stroma of spindle cell lipoma." (PMID 37401932, 2023). "For the 2 tumors with thick-walled blood vessels where spindle cell lipoma was considered in the histologic differential at the time of this review (patients 2 and 5), CD34 was negative and RB1 was retained in the adipocyte and stromal nuclei." (PMID 37131332, 2024). "Liposuction therapy is not appropriate for the rare CD34-positive spindle cell lipoma, which can be “fat-free”." (PMID 36479096, 2022). "The immunostaining is not helpful because the spindle cells of both tumours are CD34 positive, in particular CD34 is positive in about 60 % of CA and in 100 % of spindle cell lipoma." (PMID 26187500, 2015).
synovial sarcoma (25 papers, 2007 to 2026). "It has been indicated that vimentin, cytokeratin and EMA positivity, in combination with CD34 negativity, are the most useful protein biomarkers for the diagnosis of monophasic synovial sarcoma." (PMID 24348836, 2014). "Therefore 24/25 (96%) meningeal SFT and 54/55 (98%) meningeal HPC expressed ALDH1 and or CD34 whereas only 10 /163 (6%) meningiomas and 7/98 (7%) synovial sarcomas did." (PMID 24252471, 2013). "However, synovial sarcoma usually does not express CD34, and harbors the genetic hallmark of SYT/SS18 rearrangements." (PMID 35125107, 2022). "Histologic and Immunohistochemical (Anti-CD34 antibody) analysis of sample obtained by transthoraxic Tru-cut biopsy give a confident preoperative diagnosis and exclude differential diagnosis like mesothelioma, fibrosarcoma, fibrous histiocytoma, fibromatosis, synovial sarcomas." (PMID 23503999, 2013). "Determining the correct entity is aided by CD34 negativity and EMA positivity in synovial sarcomas as compared to benign SFTs." (PMID 37927755, 2023). "Immunohistochemically, most synovial sarcomas are positive for vimentin, cytokeratin and EMA, but have a lower immunoreactivity for S-100 and CD34." (PMID 22741534, 2012). "Immunohistochemical analysis demonstrated strong nuclear STAT6 expression and diffuse CD34 positivity, while epithelial, myoid/myofibroblastic, neural, and synovial sarcoma markers were negative, confirming the diagnosis of SFT." (PMID 41640935, 2026). "On the other hand, CD34 is almost always negative in both components and a positive CD34 rules out the diagnosis of synovial sarcoma." (PMID 29621151, 2018). "Immunohistochemically most synovial sarcomas were positive for vimentin, cytokeratins, and EMA and also could show lower immunoreactivity for S-100 and CD34." (PMID 25152824, 2014). "The tumor cells were found to be positive for vimentin, EMA and S100, and negative for CD34, which, in combination with the morphological profile, confirmed the diagnosis of a monophasic synovial sarcoma." (PMID 24348836, 2014). "Synovial sarcoma, fibrosarcoma, and malignant peripheral nerve sheath tumors are usually CD34 negative." (PMID 25114818, 2014). "However, synovial sarcoma has distinct histological and immunohistochemical patterns, including negative CD34 staining, that differentiate it." (PMID 41246587, 2025). "Synovial sarcomas and mesenchymal chondrosarcomas do not usually express CD34." (PMID 24252471, 2013). "All synovial sarcomas were negative for CD34 and positive for both bcl2 and CD99." (PMID 24131748, 2013). "CD34 immunoreactivity was never observed in synovial sarcomas." (PMID 24252471, 2013). "Additionally, CD34 is negative in almost all synovial sarcomas." (PMID 35655305, 2022). "Markers that are commonly expressed on synovial sarcoma cells include epithelial membrane antigen (EMA), BCL-2, and vimentin, while markers such as protein S-100, CD99, CD34, actin, and desmin are mostly negative." (PMID 40130143, 2025). "While Bcl-2 is negative, CD34 and STAT6 are negative in synovial sarcoma and can thus aid in differentiating from SFT." (PMID 32566457, 2020). "Immunohistochemically, synovial sarcomas show immunoreactivity for cytokeratins, EMA, S-100 protein, are positive for Bcl-2, O-13, Actin and negative for CD34 and Desmin." (PMID 20062586, 2009). "The expression of CD34 and the absence of a SYT-SSX1 or SYT-SSX2 fusion transcript, rules out the diagnosis of synovial sarcoma as occurred in our case." (PMID 17577399, 2007). "CD34 and STAT6 were all negative in cases of synovial sarcoma." (PMID 32566457, 2020).
synovial sarcoma (continued). "In common with other synovial sarcomas, the immunohistochemical staining demonstrated some typical findings of synovial sarcoma: the tumor cells were positive for vimentin and CD99, but negative for CD34, Bcl-2, alpha smooth muscle actin, desmin, and S-100 protein." (PMID 24969223, 2014).